BTK (Bruton tyrosine kinase)
Diseases named in the same sentence as BTK in open-access papers (continued):
Sharing a sentence is not in itself a finding about the gene and the disease.
X-linked agammaglobulinemia (continued). "X-linked agammaglobulinemia (XLA) is a primary immunodeficiency of the humoral compartment, due to a mutation in the Bruton tyrosine kinase (BTK) gene, characterized by a severe defect of circulating B cells and serum immunoglobulins." (PMID 23862092, 2013). "Moreover, the fact that neutrophils isolated from a patient with X-Linked Agammaglobulinemia (Bruton disease) were severely compromised in their ability to produce TNF-α upon stimulation by HS plus LPS further suggested a role for BTK in the stimulation of TNF-α production." (PMID 41596726, 2026). "The phenotype of X-linked agammaglobulinemia (XLA) patients and the finding that BTK inhibition blocks downstream signaling underscores BTK’s central role in the BCR signaling pathway." (PMID 40453665, 2025). "X-linked Agammaglobulinemia (XLA), due to mutations in the BTK gene, prevents the development of mature B cells." (PMID 39712011, 2024). "The discovery of non-enzymatic functions of BTK began with seminal studies aimed at elucidating the molecular mechanisms underlying X-linked agammaglobulinemia (XLA), a primary immunodeficiency disorder resulting from mutations in the BTK gene." (PMID 39062757, 2024). "Cytoplasmic tyrosine kinases BTK and ITK are essential for forming B and T cells, and loss-of-function mutations in either result in X-linked agammaglobulinemia and an increased risk of a severe, usually fatal Epstein-Barr virus infection, respectively." (PMID 38166628, 2024). "X-linked agammaglobulinemia (XLA), or Bruton’s disease, is due to mutations in Bruton’s tyrosine kinase (BTK) gene on Xq21.33-q22." (PMID 39439639, 2024). "Patients with X-linked agammaglobulinemia (XLA), a disease resulting from loss-of-function mutations in the BTK gene, lack B lymphocytes and are prone to infections." (PMID 39596040, 2024). "Based on these comparisons, it was noted that X-linked agammaglobulinemia is another differential diagnosis of THI, characterised by mutations in Bruton’s tyrosine kinase (BTK), as indicated in genetic studies." (PMID 37628357, 2023). "Five unrelated male patients from nonconsanguineous couples were identified with symptoms consistent with X-linked Agammaglobulinemia (XLA; OMIM #300755) harboring SNVs in the BTK gene." (PMID 37592284, 2023). "X-Linked Agammaglobulinemia (XLA, OMIM entry 300,755) is a classic model of predominantly antibody deficiencies caused by mutations in Bruton’s Tyrosine Kinase (BTK) gene (OMIM #300300) with a reported incidence rate of 1/100,000 or 1/200,000 live births." (PMID 35382780, 2022). "X-linked agammaglobulinemia (XLA) is an Inborn Errors of Immunity (IEI) characterized by pan-hypogammaglobulinemia and low numbers of B lymphocytes due to mutations in BTK gene." (PMID 35382780, 2022). "X-linked agammaglobulinemia (XLA, OMIM 300755), which is characterized by low B-cell counts and is associated with early-onset colitis, is caused by defects in the BTK (HGNC:1133) gene." (PMID 35743704, 2022). "Bruton's agammaglobulinemia tyrosine kinase (BTK) belongs to the Tec non‐RTK family, which is one of the largest kinase families in mammals and includes BTK, ITK, TEC, BMX, and TXK." (PMID 36254250, 2022). "X-linked agammaglobulinemia (XLA) is a humoral immunodeficiency found in males, caused by defects in BTK encoding Bruton’s tyrosine kinase, an enzyme involved in B cell maturation by transmitting signals through the pre-B and B cell receptor." (PMID 34867986, 2021). "Utilizing bone marrow-derived macrophages from BTK-deficient mice and PBMC from patients with X-linked agammaglobulinemia (XLA), this group found reduced IL-1β production and impaired inflammasome activation within mutant myeloid cells." (PMID 33818636, 2021). "BTK is renowned for its critical role in BCR signaling and was originally identified as the gene defective in X-linked agammaglobulinemia (XLA) patients." (PMID 34150760, 2021).
X-linked agammaglobulinemia (continued). "X-linked agammaglobulinemia (XLA) is a rare inheritable disease characterized by primary immunodeficiency and caused by monogenic mutations in the Bruton tyrosine kinase (BTK) gene." (PMID 33261572, 2020). "Recently, Bruton’s tyrosine kinase (BTK) has been reported to play a role in physiological inhibition of NLRP3 inflammasome activation, which explains why patients with X-linked agammaglobulinemia tend to develop Crohn’s disease (CD)." (PMID 33143375, 2020). "X-linked agammaglobulinemia (XLA, OMIM#300,300), caused by mutations in the Bruton tyrosine kinase (BTK) gene, is a rare monogenic inheritable immunodeficiency disorder." (PMID 33261572, 2020). "X-linked agammaglobulinemia (XLA), caused by a mutation in the Bruton's tyrosine kinase (BTK) gene, is rarely reported in patients with recurrent hemophagocytic lymphohistiocytosis (HLH)." (PMID 31481959, 2019). "Since the discovery of BTK mutations as the cause of X-linked agammaglobulinemia (XLA), the role of BTK in B-cell signaling has been extensively studied." (PMID 28369144, 2017). "Research over the role of Bruton’s agammaglobulinemia tyrosine kinase (BTK) in B-lymphocyte development, differentiation, signaling and survival has led to better understanding of the pathogenesis of B-cell malignancies." (PMID 24472371, 2014). "For example, X-linked agammaglobulinemia (caused by mutations in BTK) is probably not eight times more prevalent than, e.g., the autosomal-dominant CTLA4-(haplo)insufficiency or NFKB1-(haplo)insufficiency." (PMID 41347188, 2025). "Among the three children with absent KRECs, X-linked agammaglobulinemia (XLA) associated with variants in the BTK gene was diagnosed." (PMID 41459527, 2025). "X-linked agammaglobulinemia (XLA) is caused by mutation in the BTK gene, which results in very low or absent B cells." (PMID 37809070, 2023). "BTK downregulation is responsible for X-linked agammaglobulinemia (XLA), a severe primary immunodeficiency condition caused by mutations in the BTK gene, which inhibits precursor B-cells in the bone marrow from maturing, resulting in B lymphocyte insufficiency and infection vulnerability." (PMID 36903645, 2023). "X-linked agammaglobulinemia (XLA) is a primary immune deficiency resulting from the absence of Bruton’s tyrosine kinase (BTK), an intracellular signaling molecule essential for B cell differentiation and survival." (PMID 36969196, 2023). "Although the first diagnosis to be considered in male patients is Bruton's agammaglobulinemia, patients with normal BTK sequence and/or expression should be investigated with a large genetic study such as TNGS in the early period to reach a definitive diagnosis." (PMID 35719418, 2022). "While loss-of-function (LoF) mutations in the BTK gene cause the immunodeficiency X-linked agammaglobulinemia, neither inherited, nor somatic BTK driver mutations are known." (PMID 34177947, 2021). "X-linked agammaglobulinemia (XLA) is caused by defects in the gene encoding Bruton’s tyrosine kinase (BTK), characterised by the absence of peripheral circulating CD19 + B-lymphocytes and agammaglobulinemia." (PMID 34164761, 2021). "X-linked agammaglobulinemia (XLA) is the most common form of inherited agammaglobulinemia, comprising 70% of all cases, and is caused by mutations in a pivotal protein for early pre-B cell receptor intracellular signaling: Bruton’s tyrosine kinase (BTK)." (PMID 34858394, 2021). "Bruton’s tyrosine kinase (BTK) is a 77 kDa non-receptor kinase originally identified as being defective in the primary immunodeficiency X-Linked Agammaglobulinemia (XLA." (PMID 34164404, 2021). "Furthermore, Candida infections in individuals with X-linked agammaglobulinemia (XLA), a mutation in the gene encoding for Bruton tyrosine kinase (BTK) which leads to impaired peripheral B cell maturation, have been described." (PMID 33193324, 2020).
X-linked agammaglobulinemia (continued). "We have previously shown that an MS-based approach for the quantification of signature peptides for BTK, WASP, and a T-Cell marker CD3ε from tryptic digests of PBMCs can be used to screen X-linked agammaglobulinemia (XLA), Wiskott-Aldrich Syndrome (WAS), and SCID, respectively." (PMID 32296420, 2020). "The BTK gene is located on the X chromosome (Xq21.33-Xq22) and was first described in the setting of X-linked agammaglobulinemia, a disorder characterized by a lack of maturation and development of B lymphocytes and gammaglobulins due to a mutation in BTK." (PMID 29561760, 2018). "The lack of BTK in X-linked agammaglobulinemia (XLA) patients does not affect monocytes and polymorphonuclear cells (PMN) phenotype and functions." (PMID 28422989, 2017). "Loss-of-function mutations in BTK lead to X-linked agammaglobulinemia because of a complete absence of mature B cells." (PMID 25692415, 2015). "In order to rule out X-linked agammaglobulinemia, Bruton tyrosine kinase (BTK) mutation was tested and found to be negative." (PMID 26346511, 2015). "BTK is a non-receptor tyrosine kinase, the functional loss of which causes the hereditary immunodeficiency, X-linked agammaglobulinemia (XLA) - a disease that is characterized by a complete lack of mature B-lymphocytes and, consequently, serum immunoglobulins." (PMID 26415231, 2015). "X-linked agammaglobulinemia (XLA) is a primary immunodeficiency characterized by an abnormal development of B lymphocytes and severe hypogammaglobulinemia, due to a mutation in the Bruton Tyrosine Kinase (BTK) gene." (PMID 23862092, 2013). "BTK, also known as agammaglobulinemia tyrosine kinase (ATK) or B-cell progenitor kinase (BPK), is a non-receptor tyrosine kinase that was initially identified as the defective protein in human X-linked agammaglobulinemia (XLA)." (PMID 23958373, 2013). "Absence of BTK protein expression confirmed X-linked agammaglobulinemia (XLA)." (PMID 39982345, 2025). "The diagnosis was revised and five patients were excluded: one was diagnosed with X-linked Agammaglobulinemia (XLA) after NGS analysis (pathogenic mutation on BTK gene); one could not be followed up; three did not fulfill the diagnostic criteria for CVID." (PMID 37435172, 2023). "This increased risk of bleeding in patients after ibrutinib treatment is attributed to on-target BTK inhibition, as patients with X-linked agammaglobulinemia (absence of BTK expression and defects in platelet aggregation) do not develop excessively bleeding deformities." (PMID 32455989, 2020). "Agammaglobulinemia is frequently associated with a complete absence of B cells, among which X-linked agammaglobulinemia (XLA or Bruton’s disease), related to deleterious loss-of-function mutations in the Bruton Tyrosine Kinase (BTK) gene, is the leading cause." (PMID 36316777, 2022). "Patients with X-linked agammaglobulinemia (Bruton tyrosine kinase [BTK] deficiency) also had increased circulating bacterial 16S rDNA but did not exhibit prominent immune activation, suggesting that BTK may be a host modifier, dampening immune responses to microbial translocation." (PMID 34622805, 2021). "While X-linked agammaglobulinemia (XLA), due to absent Bruton's tyrosine kinase (BTK) was initially recognized to cause arrested B cell development, there are now at least 12 known molecular defects which lead to agammaglobulinemia." (PMID 32296433, 2020). "Bruton’s tyrosine kinase (BTK), a non-receptor member of TEC kinase family, is essential for B cell development as mutations in BTK cause a primary immunodeficiency X-linked agammaglobulinemia." (PMID 33322351, 2020). "For example, X-linked agammaglobulinemia (XLA) is defined by the lack of circulating B-cells and a significant decrease in serum immunoglobulins resulting from the Bruton’s tyrosine kinase (BTK) gene mutation, which can be identified through the absence of B-cells in peripheral blood." (PMID 40868091, 2025).
lymphoma (155 papers, 2011 to 2026). A malignant (clonal) proliferation of B- lymphocytes or T- lymphocytes which involves the lymph nodes, bone marrow and/or extranodal sites. "They reported that BGB-16673 had a nanomolar IC50 and effected BTK protein degradation in each of these TMD8 lymphoma cell lines, except for those with the BTK A428D mutation, suggesting that BGB-16673 interacts with BTK at or around A428." (PMID 39048721, 2024). "The absence of MYD88 mutations in WM patients has been associated with a higher risk of transformation into aggressive lymphoma, resistance to certain therapies (BTK inhibitors), and shorter overall survival." (PMID 35628381, 2022). "MYD88, CD79B, and/or BTK mutated lymphomas had a lower OS and PFS, which can mostly be attributed to the group of primary CNS lymphomas." (PMID 36051079, 2022). "They found that this mutation disrupts the inactive conformation of BTK, making the enzyme more active and leading to more aggressive lymphomas that can evade the drug." (PMID 33492229, 2021). "Mutation of genes encoding BTK are implicated in human immunodeficiency disease X-linked agammaglobulinemia (XLA), while BTK is abundantly expressed in B-cell leukemias and lymphomas." (PMID 34356110, 2021). "Inhibition of BTK can cause apoptosis in lymphoma cells, which makes BTK a critical therapeutic target." (PMID 29907126, 2018). "This multifaceted disruption of redox homeostasis significantly enhances DLBCL cell vulnerability to ferroptosis and provides a mechanistic rationale for exploiting BTK inhibitors in combination with ferroptosis-inducing therapies in high-risk, apoptosis-refractory lymphomas." (PMID 41173858, 2025). "MALT1 protease inhibitors might prove especially valuable in the treatment of lymphomas that harbor mutations in signaling effectors downstream of BTK or that have acquired resistance towards BTK inhibition." (PMID 29587428, 2018). "High expression of BTK is associated with the tumorigenesis of leukemia and lymphoma." (PMID 28946903, 2017). "However, mutations in BTK or in downstream components such as CARMA1/CARD11 can render lymphomas Ibrutinib resistant." (PMID 26540570, 2015). "In multivariable analysis, BTK inhibitor (HR=3.5, 95% CI 1.6–8.0, P=0.003), active therapy (HR=3.3, 95% CI 1.6–6.8, P=0.001), and disease non-remission (HR=2.9, 1.3–6.4, P=0.007) were independent risk factors for pneumonia development after COVID-19 infection in patients with lymphoma." (PMID 39834945, 2024). "Therefore, future studies can focus on the integration of COVID-19, SARS-CoV-2, bronchial epithelial cells, and transcriptomic analysis in lymphoma patients, especially regarding the gene networks associated with pneumonia risk when using BTK inhibitors or anti-CD20 therapies." (PMID 39834945, 2024). "BTK inhibitors are approved and in clinical use for hematological cancers such as lymphoma and leukemia, with testing underway in solid tumors." (PMID 41822319, 2026). "Similarly, the BTK inhibitor acalabrutinib and the novel combination of lenalidomide with rituximab (R2) have shown impressive results in difficult-to-treat lymphoma variants, and may offer therapeutic alternatives for PLPN patients." (PMID 41010299, 2025). "Studies have demonstrated that BTK inhibitors can enhance the survival of patients with lymphoma and CNS involvement, and orelabrutinib can effectively and safely treat primary CNS lymphoma." (PMID 40842532, 2025).
lymphoma (continued). "Comp-10 represents a promising therapeutic strategy for ALK-driven and BTK inhibitor-resistant lymphomas and potentially other tyrosine kinase-driven malignancies." (PMID 41154443, 2025). "We demonstrated that KAT/3BP exhibits both in vitro and in vivo cytotoxic activity in lymphoma models as a single agent, with efficacy maintained in models harboring secondary resistance to BTK, BCL2, and PI3K inhibitors." (PMID 40563683, 2025). "Unlike classical active-site inhibitors such as mycophenolic acid (MPA), Comp-10 decreases IMPDH1/2 protein levels, blocks filament (rod/ring) formation, and inhibits the growth of ALK and BTK inhibitor-resistant lymphoma cells." (PMID 41154443, 2025). "This hallmark of B cell–derived lymphoma is considered an oncogenic and prosurvival signal and underlies the rationale for using BCR inhibitors to target downstream kinases such as BTK, SYK, and PI3Kδ." (PMID 38048228, 2024). "Ibrutinib, FDA-approved lymphoma agent, inhibits Bruton tyrosine kinase (BTK) and has previously been shown to independently impair aortic endothelial adhesion and increase rodent glioma model survival in combination with cytotoxic therapy." (PMID 38589905, 2024). "The advent of BTK inhibitors ushered in a promising era in lymphoma therapeutics owing to the role played by BTK in the BCR pathway in the pathogenesis of lymphomas." (PMID 39062757, 2024). "NX-5948 is another heterobifunctional small molecule degrader targeting BTK with therapeutic efficacy in lymphoma patients." (PMID 39169396, 2024). "BTK inhibitors, approved for the treatment of leukemia and lymphoma, raise intriguing questions about their potential role in atherosclerosis patients." (PMID 38716195, 2024). "Previous studies have shown high BTK expression on glioma cells and ibrutinib’s efficacy to hinder lymphoma and other solid tumors progression through inhibition of the BTK/BMX pathway." (PMID 38589905, 2024). "So, for lymphoma patients, particularly those with B-cell non-Hodgkin lymphoma, especially those receiving BTK inhibitors or anti-CD20 therapy, it is recommended to implement personalized protective measures." (PMID 39834945, 2024). "The pivotal role of BTK in BCR signaling and B cell lymphoma pathogenesis has led to the development of BTK inhibitors as targeted therapies, which are now a frontline therapy for many lymphoma subtypes." (PMID 39062757, 2024). "As a result, the abnormal activation of BTK can lead to several B-cell malignancies, including various types of leukemias and lymphomas, as well as autoimmune disorders such as rheumatoid arthritis (RA) and multiple sclerosis (MS)." (PMID 39777345, 2024). "Our bioinformatics analysis revealed elevated expression of epigenetic regulator genes, including HDAC and BTK, in lymphoma tissues." (PMID 38381215, 2024). "The discovery of new functions of BTK revealed a need for new treatment avenues for patients with BTK-dependent lymphomas." (PMID 39062757, 2024). "In recent years, BTK inhibitors have shown great potential in treating lymphomas derived from various B cells because of their strong targeting ability and relatively few side effects." (PMID 39777345, 2024). "This is particularly important as the combination regimen is likely to be effective in specific subgroups of lymphoma with an enrichment in the BTK pathway." (PMID 38555311, 2024). "Recently, it has shown superior survival compared with BBB‐penetrating chemotherapy in lymphoma patients with CNS involvement, indicating the promising potencies of BTK inhibitors to treat CNS lymphoma." (PMID 37929016, 2023). "In mucosa-associated lymphoid (MALT) lymphoma, the chronic activation of the CD79B/BTK pathway enhances the proliferation of lymphoma cells." (PMID 37622116, 2023). "It effectively inhibits the BTK signaling pathway in human lymphoma cells, suppressing their proliferation, inducing cell cycle arrest, and promoting apoptosis in vitro." (PMID 37929016, 2023).